CD68 (CD68 molecule)
Diseases named in the same sentence as CD68 in open-access papers (continued):
Sharing a sentence is not in itself a finding about the gene and the disease.
tumor (continued). "Similar dynamic change in Siglec-15 and CD68 levels were found in GL261 allografts, with the peak expression level observed on Day 14 after tumor implantation." (PMID 37234161, 2023). "We detected the immune cells in tumor microenvironment of 32 TNBC pathological tissue specimens using mIF, which included marker PanCK, CD8, HLA-DR, CD68, CD56." (PMID 37219794, 2023). "As expected, in TNBC tumor sections, TAMs were localized in the FN-EDA-rich matrix and pSTAT3 (Tyr705) was detected in the CD68+ macrophages." (PMID 36922898, 2023). "CD206+ and CD68+ were also increased, indicating that PDT treatment triggers macrophage infiltration and inflammatory response in the distant tumor sites." (PMID 36944686, 2023). "To observe the effect of HK010 on TAMs, we detected the expression of CD68 and CD163 in tumor tissues." (PMID 37259060, 2023). "To further verify this notion, we examined CD68, IL‐1β, CD8, and granzyme B, a cytotoxic executor, in clinical tumor tissues of HG‐SOC patients with fluorescence multiplex immunohistochemical analysis." (PMID 37009412, 2023). "Multiplex immunofluorescence analysis in two of the analysed patients also showed CD68+ macrophage populations (specifically CD68+CD163+ myeloid cells expressing PD-L1) after CAN-3110 treatment, particularly in perinecrotic tumour regions." (PMID 37853118, 2023). "Based on scRNA-seq results, we conducted mIF staining of T cells (CD3, CD4 and CD8), macrophages (CD68) and CCL4, which further indicated the differential distribution of immune cells between tumor thrombus and primary tumor." (PMID 37244923, 2023). "CD68 was found predominantly in and around pan-cytokeratin positive (CK+) tumor nests, whereas CD163 was expressed more consistently, throughout the tumor stroma." (PMID 38322012, 2023). "To further validate, we performed Immunofluorescence (IF) staining for MMP9 and CTSK in the tumor patient tissues and found that both MMP9 and CTSK had a co-localization with CD68." (PMID 38123589, 2023). "In contrast, significant correlations were found for FAP, vimentin, CAIX, CD68 and CD44, thus indicating that tumoroids are able to retain the inter-tumor heterogeneity present in the tumor tissues." (PMID 37736770, 2023). "They decreased toward the IM, whereas M2‐like (CD68+CD163+ and CD68+CD163+CD206+) TAM levels were less dense and restricted to the tumor margins." (PMID 36998102, 2023). "We found that the mRNA expression CD68, CD69 and CYP27A1 levels were significantly downregulated, and PLTP levels was significantly up regulated in tumor samples." (PMID 37880277, 2023). "In this study, we found that macrophages enriched in tumor tissue exhibited high expression of CD163 and CD68 (M2-like macrophages)." (PMID 35812401, 2022). "The results showed that CD68 expression positively correlated with the expression of LAIR1, HAVCR2, LGALS9, and PD-1 (PDCD1) in most of the 33 tumor types." (PMID 35550532, 2022). "A comprehensive correlation matrix was created to seek the correlates of DTICs, including CD3+, CD4+, CD8+, CD68+, and FOXP3+ cells in central-tumor and invasive-margin areas." (PMID 35443723, 2022). "We next performed IHC immunostaining for several established markers of distinct immune subclasses in human MPNST tumor tissue, including CD45 (pan-leukocyte), CD3 (T cells, CD4+ and CD8+ subsets), CD68 (macrophages/monocytes), and CD20 (B cells)." (PMID 35852856, 2022). "After treatment with ADT, CD68+ and CD163+ macrophage infiltration was increased in the tumor tissues of patients." (PMID 36439479, 2022). "For each tumor, we selected 12 regions of interest (ROIs) that were enriched with tumor cells (smooth muscle actin positive, green), T cells (CD3 positive, pink), and macrophages (CD68 positive, yellow) for RNA sequencing." (PMID 36028490, 2022). "In the adjacent tumor tissue homogenates, we determined PD-L1-mRNA, PD-1-mRNA, CD3-mRNA and CD68-mRNA levels." (PMID 35184226, 2022).
tumor (continued). "The distribution of immune cell density showed a wider interquartile range (IQR) for all tumour regions (CT, FR, ME) than in the normal colorectal epithelium for all assessed antigens (CD8, GZMB, CD68, CD163)." (PMID 36114487, 2022). "Increased infiltration of both CD68+ and CD163+ TAMs in tumor mass correlated with decreased survival of 174 patients with gastroesophageal adenocarcinoma from Sweden." (PMID 36686729, 2022). "First, we compared the internal areas of the primary tumor and liver metastases, found that 8 markers (CD8, Foxp3, CD68, CD163, CD20, CD11c, VEGFR-2, PD-L1) had higher expression in TF than TC region in both primary tumor and liver metastases (p < 0.05)." (PMID 36195882, 2022). "A strong immune response to the cancer, as measured by high tumor influx of CD68(+), CD3(+) or Foxp3(+) cells, predicts better long-term overall survival, especially Foxp3(+) in HPV(+) tumor patients." (PMID 36289746, 2022). "Remarkably, the abundance of TIICs, including CD8+, CD4+, CD68+, CD20+ and CD66b+ cells, significantly increased with the increase in CPS, indicating a ‘hotter’ tumour immune environment." (PMID 35982052, 2022). "Specially, we stained CD68 with green fluorescence and stained CD86 or CD163 with red fluorescence in the tumour tissues by IF co‐localization assay." (PMID 34964155, 2022). "With a view to the tumor subregions, the invasion front showed the highest infiltration of both immune cell types, CD8+ T cells and CD68+ macrophages, compared to the stroma and the epithelium in both NMSCs." (PMID 35463364, 2022). "In general, higher levels of CD163+ TAMs compared to CD68+ are detected across all TET subtypes, while CD163+ population also exhibits a progressive enrichment along with the aggravation of tumor malignancy." (PMID 35887212, 2022). "Based on the obtained expression profiles, the primary tumor tissues were categorized into immunological cold or hot tissues (presence of CD8α, CD11c, CD16 and CD68); the impact of immune cell infiltration on event-free survival was established." (PMID 36139700, 2022). "In the primary tumor, the expression of all 12 markers (CD8, CD68, Foxp3, CD11c, CD163, CD66b, CD56, CD20, PD-L1, VEGFR-2, Ki67, IFN-γ) in the PT region was lower than that in the TF region (p < 0.05)." (PMID 36195882, 2022). "Cytokeratin (CK) can label the tumor cells of HNSCC and normal epithelial cells, which can discriminate from the immune cells of the tumor microenvironment, such as CD3 labeling T lymphocytes, CD20 meaning B lymphocytes, and CD68 labeling macrophages." (PMID 36499755, 2022). "Proficient MMR (pMMR) tumours showed a significantly higher abundance of total CD4+, CD68+, CD20+ and CD66b+ cells than dMMR tumours." (PMID 35982052, 2022). "We confirmed the restriction of SOX2 expression to tumor cells, PTPRC/CD45 to immune cells, SPI1/PU.1, CD68, and CD163 to ‘macrophages’, CD3G to ‘T cells’, and OLIG1/2 and MBP to oligodendrocytes." (PMID 35973991, 2022). "The current study is aimed at testing CD4, CD8, CD68, and MMP9 immunohistochemistry of DLBCL activities with the prognosis of the tumor." (PMID 35083113, 2022). "We also used CD68, a pan macrophage marker, and CD206, a tumor-promoting M2 macrophage marker for IHC labeling." (PMID 35626709, 2022). "Consistently, PTX3 was more co‐expressed with CD68 and CD163 in tumor tissues than in paratumor tissues." (PMID 35855654, 2022). "We identified a number of protein and RNA transcript level differences within the tumor microenvironment: STING and CD68 were upregulated in tumors over TAS, suggesting enhanced immune responses targeting specific tissue types." (PMID 36230846, 2022). "Once again by using the median density in the TP25μm zone at the tumour centre as the cut-off, patients were classified as either high or low for CD8, GZMB and CD68 respectively." (PMID 36114487, 2022).
tumor (continued). "In detail, we checked CD8+ T cells, CD68+ TAMs, and CD58+ NK cells in the tumor parenchyma (TP), stroma (TS), paracancerous tissue (PT), and nontumor tissue (NT)." (PMID 35150094, 2022). "Our results indicate a significant increased number of both CD68+ and CD163+ cells in the center of the GBM tumor with respect to the outside." (PMID 36611806, 2022). "Some well-known marker genes were used to identify cell types, such as EPCAM and KRT19 for tumor cell, COL1A1 and ACTA2 for CAF, CD3D and CD3E for T cell, and CD68 and CD14 for macrophage." (PMID 36499343, 2022). "Immunohistochemistry examination of this tumor showed CD3-, CD20-, and ALK-1-negative and CD30- and CD68-positive stains." (PMID 35685060, 2022). "The present work investigated the influence of the different factors VEGF, Ki-67, COX2, M-CSF, GM-CSF, CD68, and CD163 on tumor volume and growth as well as on clinical parameters, such as age and hearing, in a cohort of 173 patients using mRNA data and IHC." (PMID 36139588, 2022). "We observed that the majority of the ER+ high miR-18a-expressing samples expressed MMP9, and these tumor specimens also expressed a higher CD4/CD8 and a higher CD206/CD68." (PMID 35626709, 2022). "CD68+ CD206- M1 macrophages participate in antigen presentation, inflammation, and anti-tumor activity." (PMID 36237314, 2022). "The results indicated that the expression of CD68 was positively related to the abundance of B cells, CD4+ and CD8+ T cells, dendritic cells, macrophages, and neutrophils in many tumor types." (PMID 35550532, 2022). "We found prognostic significance of the CD68, CD163 and CD8-positive cell number in the tumor stroma." (PMID 35884821, 2022). "GBM tissue samples were subjected to immunohistochemistry for CD68 and CD163 in order to evaluate total and M2 macrophages, respectively, in both the center side of the tumor and in the healthy surrounding areas." (PMID 36611806, 2022). "Immunohistochemistry (IHC) confirmed that the tumor inflammatory infiltrate was composed, at least, of T cells (CD3+), macrophages (CD68+), and neutrophils (CD15+)." (PMID 35192545, 2022). "pCR/MPR patients displayed significantly higher density of CD3+, CD3+CD4+, CD20+, CD56 bright cell subsets and more tertiary lymphoid structures and significantly lower density of PD-L1+CD68+ and CD3+CD4+Foxp3+cells in the tumor or stroma." (PMID 36275670, 2022). "Tumor cell-macrophage hybrids express both macrophage (CD14, CD68, CD163, CD204, and CD206) and tumor-specific markers (ALCAM, MLANA, KRT, EpCAM, CXCR4, and CD44)." (PMID 35242760, 2022). "This analysis revealed that up-to 25% of cells in the tumor expressed high levels of TRIB1 protein and that about 42% of these cells were also positive for the macrophage marker CD68." (PMID 35664073, 2022). "Regarding expression changes with respect to grouped tumor size, weak statistically significant downregulation of CD115 (p = 0.05; FC = −1.6), CD68 (p = 0.04, FC = −1.3) and CD137L (p = 0.04, FC = −1.7) was seen in larger lesions (T3/T4)." (PMID 35406584, 2022). "Considering immune infiltration, tumour areas with a higher FDG uptake had higher levels of T-lymphocytes (CD3+ and CD4+/CD8+) and macrophages (CD68+/CD163+) compared to areas with a lower uptake." (PMID 36143097, 2022). "The results demonstrated significantly higher numbers of CD14+ and CD68+ cells in the tumour infiltrate of PDLIM2-positive tumours and in PDLIM2-positive stroma than in either PDLIM2-negative tumours or stroma." (PMID 36531051, 2022). "For example, in gastric cancer, tumor-infiltrating CD8+ T cells and CD68+ macrophages predict prognosis." (PMID 35203636, 2022). "The number of tumor-infiltrating CD4+, CD8+, Foxp3+lymphocytes, CD68+, CD163+macrophages in pre-treatment endoscopic biopsy samples were evaluated to investigate their predictive value for multidisciplinary treatment." (PMID 35658848, 2022).
tumor (continued). "High tumor infiltration of CD3, Foxp3 and CD68-positive cells predicted better twenty-year OS, with and without HPV stratification." (PMID 36289746, 2022). "The BCC micrograph slides are matching in all images and show a stronger staining pattern in the tumor invasion front compared to the tumor center for both CD8 and CD68." (PMID 35463364, 2022). "CD8+, GZMB+, CD68+ and CD163+ cells showed significant correlation throughout the majority of assessed tumour regions (centre, front and microenvironment)." (PMID 36114487, 2022). "The expression of CD68 and NOS2 was stronger in tumor stroma than in normal tissue but weaker in tumor parenchyma than in normal tissue." (PMID 35646079, 2022). "The maximum intensity projection of multiplexed data was used to determine the patch type between tumor (Pan-Keratin+E-cadherin), stroma (COL1+SMA), CD8ɑ, M1 (HLA-DR+CD68), and M2 (CD68+CD163+CD206)." (PMID 36050391, 2022). "The 4 markers CD4, CD8, CD68, and MMP9 were compared to the different prognostic markers aimed at detecting any effect of these immune marker expressions on the prognosis of the tumor." (PMID 35083113, 2022). "Consistently, our results showed that the high expression of PLIN2 in the tumor center was related to advanced TNM stage, which featured as more infiltration of CD68+TAMs." (PMID 35372038, 2022). "In particular, an increased density of total CD8+ T lymphocytes, CD68+ macrophages and CD163+ TAMs was observed in the peri-tumoral stroma and within the tumor nests." (PMID 36123711, 2022). "We next examined alterations in tumor-infiltrating leukocyte subtypes, specifically CD3-positive T-cells, CD68-positive macrophages, and neutrophils (neutrophil elastase-positive cells)." (PMID 35751111, 2022). "Instead of clustering with cytotoxic T cells, tumor cells in A-CIA cluster with macrophages (CD68) and B cells (CD20), both of which can produce IL-10 (also found in the A-CIA tumor cluster)." (PMID 35379804, 2022). "The number of CD8+, FOXP3+, CD68+, CD163+ and PMNs was highly variable, however, all immune cells prevailed in stroma when compared to tumor nests." (PMID 35681497, 2022). "The same tissue neighborhood analysis was applied between tumor/epithelial, stromal, CD8+, and CD68+ regions and revealed a similar trend for the immune infiltration spectrum." (PMID 36050391, 2022). "We used IHC to evaluate the expression of CD169 and CD68 in RLNs and CD8 in tumor tissues obtained from patients with OSCC who underwent radical resection." (PMID 35044489, 2022). "The results show highly significant differences in terms of CD8+ T-cell and CD68+ macrophage infiltration in BCC and cSCC and indicate cSCC as a highly immunogenic tumor." (PMID 35463364, 2022). "The mean survival time for patients with tumours low for both stromal CXCL8 and CD68+ infiltration was 167 (95% CI: 150–184) months compared to 156 (95% CI: 141–170) months for one high and 122 (95% CI: 104–141) months for both low." (PMID 35879507, 2022). "He at al. also identified that the intensity of the infiltration of CD68+ and CD163+ macrophages was positively correlated with lymph-node involvement and tumor size." (PMID 36230558, 2022). "The IHC staining of CD8+ T cells, CD4+T cells, NK1.1+ NK cells, CD68+TAM, FOXP3+Treg cells and CD11C+ DCs in the tumor tissues also showed a similar trend." (PMID 35525959, 2022). "We identified higher proportions of CD68+, CD68+CD163+, and CD68+CD206+ TAMs in tumor tissue than in the adjacent area (t-test, p < 0.05)." (PMID 36230558, 2022). "We also evaluated the tumor microenvironment topography of FOXP3+ Tregs and CD68+ TAMs, since their immunosuppressive properties counterpoise the anti-tumor effect of cytotoxic CD8+ T-lymphocytes." (PMID 35547873, 2022). "CD68+TAM infiltration and accumulation in tumor results in tumor progression and adverse prognosis in numerous cancers." (PMID 36686729, 2022).
tumor (continued). "IHC for CD103, CD68, CD3, and CD4 was also assessed in non-tumor mice to determine the effects of RL on immune function without cancer." (PMID 35847848, 2022). "Expression of the TAM marker CD68 and the M2 marker CD206 were analyzed in serial sections of tumor tissues from the patients." (PMID 36270983, 2022). "We found positive staining for the FAM49B protein in the tumor cells of HNSCC, and the co-expression of FAM49B and CD3, CD20, and CD68 demonstrates that FAM49B can express in the T cells, B cells, and macrophages around SCC." (PMID 36499755, 2022). "We have furthermore shown that high levels of tumor CD3(+), CD68(+) cells and TIL FoxP3 predict better twenty-year OS, both overall and among non-OPSCC-related deaths." (PMID 36289746, 2022). "The tumor was positive for immunomarkers CD31, CD34, D2-40, CD68, Ki-67 (1–2% positive nuclear staining) as well for smooth muscle markers SMA (Smooth muscle actin) and Desmine." (PMID 34404967, 2021). "Tumour-infiltrating immune markers (CD3, CD4, CD8, CD20, CD56, CD68, PD-1, PD-L1) were assessed by immunohistochemistry." (PMID 33087896, 2021). "There was a strong positive correlation between the infiltration of CD20+ B cells, cytotoxic CD4+ and CD8+ T cells, regulatory FOXP3+ T cells, and CD68+ and CD163+ macrophages in both stroma and tumor nests." (PMID 33494389, 2021). "Tumor infiltrating lymphocytes (TILs) were differentiated against tumor cells based on expression of CD3, CD20, or CD68 on IHC staining." (PMID 35938052, 2021). "Further compartmentalization of the tumor compartment into PT Tumor (CD14 p = 0.001; CD68 p < 0.001; CD163 p < 0.001) and IT Tumor (CD14 p < 0.001; CD68 p < 0.001; CD163 p < 0.001) showed similar results." (PMID 34194435, 2021). "In summary, the present study confirmed that the infiltration of CD68+ TAM and CD163+ M2 TAM had obvious difference in tumor tissue of CC and normal cervical tissue." (PMID 33928349, 2021). "The prevalence of CD14+, CD68+ and CD163+ cells was higher in grade 3 tumors than in grade 1 tumors, both in PT Tumor and IT Tumor compartments." (PMID 34194435, 2021). "Ultrasound-guided biopsy revealed diffuse infiltration of undifferentiated tumor cells and immunohistochemistry (IHC) indicated that the tumor was positive for myeloperoxidase (MPO), cluster of differentiation (CD) 34, CD43, CD68, CD117, and Ki67." (PMID 34579724, 2021). "The localised KLK6 expression in tumour cells (identified by KRT19) and macrophages (represented by CD68) in the invasive areas underscores the potential for KLK6-targeted inhibitors that interfere with tumour-biological events in a context-dependent manner." (PMID 34439122, 2021). "In the tumor capsule, 80% of dendritic cells, 65% of CD45 positive cells, 65% of CD11b positive cells, and 10% of CD68 positive cells were detected." (PMID 33921688, 2021). "We divided NPC patients into three subgroups based on EBV and HPV status (EBV−/HPV-, EBV+/HPV-, EBV+/HPV+) and investigated MIF, CD11c, CD68, and CD163 IF scores in tumor nest and tumor stroma." (PMID 34407796, 2021). "There was a strong positive correlation between the infiltration of CD20+ B lymphocytes and other immune profiles (i.e., CD4+, CD8+, and FOXP3+ TILs, and CD68+ and CD163+ macrophages) both in stroma and tumor nests." (PMID 33494389, 2021). "We analyzed the absolute count and percentage of CD45+ leucocyte, CD68+ macrophage and CD163+ M2 type macrophages in the tumor core, perivascular area and tumor infiltration zone." (PMID 34654395, 2021). "In the tumor capsule, 50% of dendritic cells, 30% of CD45 positive cells, 20% of CD11b positive cells, and 5% of CD68 positive cells were detected." (PMID 33921688, 2021). "B7S1 protein was found to be highly expressed in CD45+CD68+ myeloid cells, whereas its putative receptor was expressed in CD8+ tumor-infiltrating lymphocytes (TILs)." (PMID 34307455, 2021).